IL6 (interleukin 6)
Diseases named in the same sentence as IL6 in open-access papers (continued):
Sharing a sentence is not in itself a finding about the gene and the disease.
Headache (continued). "In addition, the IL-6 levels in the headache-only group (B) were significantly higher than those in the no-symptom group (A) (+p = 0.008, B vs A)." (PMID 26968975, 2016). "This cohort should include comprehensive biomarker collection, including serial measurements of inflammatory cytokines (IL-6, TNF-α, IL-1β), CGRP levels, markers of blood–brain barrier disruption, and genetic polymorphisms that may influence drug metabolism or headache susceptibility." (PMID 41516139, 2025). "Chemotherapy activates glial cells, such as microglia and astrocytes, which release pro-inflammatory cytokines, including IL-6, TNF-α, and IL-1β, sensitizing pain pathways and contributing to headache development." (PMID 41516139, 2025). "Omega-3 fatty acids (which have known anti-inflammatory effects by generating resolvins) consistently improved headache outcomes and raised IL-4/lowered IFN-γ 9, as well as reduced IL-6 in combination with curcumin." (PMID 41377228, 2025). "Another research reported findings of decreased IL-1β and elevated IL-6 levels during headache attacks and also demonstrated that IL-1β had the highest discriminative value between patients with headaches and controls compared to CRP and IL-6." (PMID 37176049, 2023). "The same group published another case–control study including 88 patients, where serum levels of HMGB1, NLRP 3, IL-6, angiotensin II and ACE 2 were higher in patients with headache during COVID-19." (PMID 35915417, 2022). "Regarding the central tendency measures, in the comparison of the crude median values of cytokines, we observed that patients with headache had higher median values of GROa, IFN-gamma, IL-10, IL-13, IL-15, IL-17a, IL-21, IL-22, IL-27 and IL-6." (PMID 34088273, 2021). "Activation of resident mast cells in the meninges and release of proinflammatory cytokines such as IL-1β, IL-6, TNF-α and several chemokines have been proposed to play major roles in the progression of migraine headache." (PMID 34615455, 2021). "This combination treatment improves the overall success rate of treatment, reduces scores related to nasal symptoms, such as congestion and runny nose, alleviates symptoms like headache and olfactory disorders, and decreases inflammatory indicators like TNF-α and IL-6." (PMID 39612467, 2024). "A clinical trial analyzed IL-1beta, IL-6, and TNF-alpha in 24 h urine samples of female migraineurs during menstrual and non-menstrual migraine attacks and headache-free periods and compared them with those of non-headache controls." (PMID 36835524, 2023). "While some studies have reported an association between the occurrence of headache and pro-inflammatory substances such as NLRP3, HMGB1, and interleukin 6, this has not been the case with all authors." (PMID 34979899, 2022). "They found that the serum level of high mobility group box-1 (HMGB1), Nod-like receptor pyrin domain-containing 3 (NLRP3), angiotensin-converting enzyme 2 (ACE2), and IL-6 was significantly higher among COVID-patients with headache compared patients without it." (PMID 35911910, 2022).
hypothyroidism (39 papers, 2014 to 2025). Abnormally low levels of thyroid hormone. "Conversely, when we treated hypothyroidism as an exposure factor, we detected a causal association between hypothyroidism and 13 inflammatory cytokines (IL-13, IL-16, IL-2rα, IL-6, IL-7, IL-9, G-CSF, SCGF-β, IP-10, MIG, MIP-1β, SDF-1α, and TNF-α)." (PMID 38317717, 2023). "The increased number of Th17 cells, activated by rising IL-6 levels, secrete cytokines that influence the autoimmune status and are involved in the development of hypothyroidism in pregnancy." (PMID 41573549, 2025). "In individuals with hypothyroidism, papanas found a favorable correlation between IL-6 levels and thyroxine replacement dosage." (PMID 40237055, 2025). "TSH, TPOAb, CRP, percentage of Th17 cells, Th17/Treg ratio, IL-2, IL-6, IL-10 and TNFα levels increased significantly in the hypothyroidism group compared to the control group, and FT4 levels and percentage of Treg cells decreased significantly." (PMID 41573549, 2025). "One is by the development of (sub)clinical hypothyroidism (TAI is the most frequent cause of hypothyroidism) and another via inflammatory pathways involving IL-6 and TNF-α; both pathways can lead to insulin resistance (IR)." (PMID 35195084, 2022). "In a previous study, the levels of TNF-α, IL-6, and other cytokines increased in hypothyroidism rats." (PMID 36514041, 2022). "Together, these molecular ways sustain a proinflammatory response by the kallikrein-kinin system, by IL-6 signaling, and by innate inflammatory response that led to the hypothyroidism symptoms." (PMID 35330001, 2022). "Hypothyroidism resolved after treatment with levothyroxine; however, hypogonadism and hyperprolactinemia normalized after anti-IL-6 therapy." (PMID 31453020, 2019). "We therefore investigated serum levels of T4 and proinflammatory cytokine IL-6 in P5 littermates and found that Trpm7-intestine KO individuals developed severe hypothyroidism and had high circulating levels of IL-6." (PMID 30770447, 2019). "High TSH levels, in response to hypothyroidism, induce the release of IL-6 via NF-κB activation." (PMID 40672362, 2025). "The inflammatory signs observed in patients with hypothyroidism are thought to be related to the interplay between IL-6, TNF-α, and IL-1, which may be linked to elevated levels of HCRP during hypothyroidism." (PMID 39600704, 2024). "Additionally, CKD patients are at increased risk of hypothyroidism, likely due to hemodialysis, impaired iodine clearance, or inflammatory markers like CRP and IL-6, which cause endothelial damage and affect thyroid function." (PMID 39650928, 2024). "Additionally, it is worth noting that IL-6 levels have the potential to serve as an indicator of the extent of hypothyroidism." (PMID 38317717, 2023). "All these processes, if dysregulated, have the potentiality to induce a pro-inflammatory response by IL6 signaling, kallikrein-kinin system activation, and innate inflammatory response that could be considered responsible for hypothyroidism symptoms." (PMID 35330001, 2022). "The study with 91 patients with HT (42 with hypothyroidism and 49 euthyroidism) and 50 healthy people found that the levels of inflammatory factors, including interleukin 6 (IL-6), 12, 10 and tumor necrosis factor-α (TNF-α) were lower in the control group compared to the HT group." (PMID 35743024, 2022). "For example, tocilizumab can target inhibit IL-6 in order to prevent the increased of IL-6 and stop related toxicities; patients with high titer of TgAbs and TPOAbs who developed to grade 2 hypothyroidisms early take a moderate dosage of L-T4 therapy throughout." (PMID 33123120, 2020).
hypothyroidism (continued). "IL-6 level might be correlated with hypothyroidism severity because serum IL-6 level has been positively correlated with LRT dose and negatively correlated with FT4 level in hypothyroidism due to autoimmune thyroiditis." (PMID 26100072, 2015). "Hypothyroidism may result in inadequate protection to cells resulting in increased oxidative stress (OS), which in turn has been closely related to inflammation markers such as IL-6 and CRP." (PMID 38330593, 2024). "We found that CRP, IL-2, IL-6 and TNF-α levels were increased in pregnant women with hypothyroidism in the first half of pregnancy." (PMID 41573549, 2025). "For instance, the administration of T3 normalized the increased expression of the pro-inflammatory cytokines IL-1β, IL-6, and TNF-α in the hippocampus of rats with hypothyroidism." (PMID 39513900, 2024). "A previous study showed that hypothyroidism rats had increased levels of TNF-α, IL-6, and other cytokines." (PMID 36514041, 2022). "The levels of TSH, hsCRP, IL-10, IL-6, TNF-α, TC, LDL, FFA and ApoB in the pregnancy hypothyroidism group were higher than those in the control group (P <0.05)." (PMID 36275023, 2022). "In this study, we found that the levels of hsCRP, IL-10, IL-6 and TNF-α in pregnant women with clinical hypothyroidism during pregnancy were significantly higher than those in the control group." (PMID 36275023, 2022). "Hypothyroidism resulted in significant increases in the plasma inflammatory markers CRP and TNF-α and IL6, whereas reversing the hypothyroid state further increased these levels." (PMID 25333636, 2014). "Additionally, hs-CRP, IL-2, IL-6 and TNF-α levels were elevated in the hypothyroidism group, suggesting an inflammatory response in these patients during the first half of pregnancy, aligning with previous studies." (PMID 40443669, 2025). "The levels of hsCRP, IL-6 and TNF-α in SIBO-positive pregnant women with clinical hypothyroidism after treatment with probiotics combined with prebiotics were significantly lower than before treatment, and the concentrations of TC and LDL were also lower after treatment." (PMID 36275023, 2022).
pancreatic ductal adenocarcinoma (39 papers, 2016 to 2025). An infiltrating adenocarcinoma that arises from the epithelial cells of the pancreas. "Here, we found that, specifically, the IL6 high iCAFs co-occur with the stress-associated cancer cells, complementing a recent spatial transcriptomics study of pancreatic ductal adenocarcinoma." (PMID 35196078, 2022). "Pancreatic ductal adenocarcinoma develops within a dense desmoplastic stroma characterized by activated fibroblasts and tumor-associated macrophages that secrete pro-inflammatory cytokines such as interleukin-6 (IL-6) and tumor necrosis factor-α (TNF-α)." (PMID 41303856, 2025). "In pancreatic ductal adenocarcinoma, CAFs increase the resistance to chemotherapeutic drugs by secreting factors such as IL-6." (PMID 39165997, 2024). "Upregulation of circCUL2 expression induces an activated CAF phenotype, which functions as a ceRNA and modulates the miR-203a-3p/MyD88/NF-κB/IL6 axis, then promotes the progression of pancreatic ductal adenocarcinoma (PDAC) by secreting IL-6." (PMID 37819576, 2023). "Penny and colleagues also reported that pancreatic ductal adenocarcinoma produced TAMs expressing both M1 (IL‐1β, IL6, and TNF‐α) and M2 (CD163, CD206, and Arg1) markers." (PMID 37688511, 2023). "For example, Interleukin-6 (IL6) has been used in pancreatic ductal adenocarcinoma (PDAC) to describe inflammatory CAFs (iCAFs)." (PMID 37626157, 2023). "IL-6-induced STAT3 phosphorylation in pancreatic ductal adenocarcinoma (PDAC) was suppressed by blocking IL-6R leading to the attenuation of STAT3 activation in TME toward enhanced sensitivity of cancer cells to chemotherapy." (PMID 36091805, 2022). "IL-6/Stat3 have also been implicated in pancreatic ductal adenocarcinoma (PDAC), and paracrine IL-6/Stat3 signaling was shown to regulate the effects of PSCs in matricellular fibrosis and tumor progression." (PMID 35211358, 2022). "Recently, IL-6 and programmed death-1-ligand 1 (PD-L1) antibody blockade combination therapy decreases pancreatic ductal adenocarcinoma (PDAC) tumor progression and increases the percentage of intratumoral effector T cells." (PMID 31731674, 2019). "Indeed, Penny and colleagues also reported that pancreatic ductal adenocarcinoma-generated TAMs expressed both M1 (IL-1β, IL6, and TNF-α) and M2 (CD163, CD206 and Arg1) markers." (PMID 30927925, 2019). "In addition, in pancreatic ductal adenocarcinoma cells, interleukin-6-mediated Stat3 activation induced Nrf2 signaling to promote EMT)." (PMID 28758930, 2017). "Within pancreatic ductal adenocarcinoma (PDAC), over-activated pancreatic stellate cells (PSCs) secrete substantial amounts of GAL1 and interleukin-6 (IL-6)." (PMID 38946426, 2024). "This categorisation is exemplified by the induction of IL‐6+ CAFs (iCAF) and α‐SMA+ CAFs (myCAF) from quiescent pancreatic stellate cells in pancreatic ductal adenocarcinoma through IL‐1 and tumour growth factor‐beta (TGF‐β) stimulation." (PMID 38148640, 2023). "Interleukin 6 (IL-6), Oncostatin M (OSM), and downstream effector STAT3 are pro-tumorigenic agents in pancreatic ductal adenocarcinoma (PDAC)." (PMID 36495330, 2023). "Another study showed the upregulation of IL-6, IL-1b and VEGF in pancreatic ductal adenocarcinomas in the presence of high concentrations of G-CSF." (PMID 35022523, 2022). "Pancreatic ductal adenocarcinoma (PDAC) is notorious for its aggressive progression and dismal survival rates, with this study highlighting elevated interleukin 6 (IL-6) levels in patients as a key marker of increased disease severity and a potential prognostic indicator." (PMID 38672257, 2024). "In pancreatic ductal adenocarcinoma, application of IL6R blocking antibodies through inhibiting IL6 signaling could shift the tumor microenvironment from a chemoresistant state to a chemosensitive state, which was accompanied with reduced STAT3 activation." (PMID 33714953, 2021).
pancreatic ductal adenocarcinoma (continued). "We examined whether elevated plasma C-reactive protein (CRP), carbohydrate antigen (CA) 19-9, interleukin-6 (IL-6) and YKL-40, individually or combined, can identify poor survivors among patients with pancreatic ductal adenocarcinoma (PDAC)." (PMID 34572824, 2021). "However, other proteins such as TWEAK (tumor necrosis factor ligand superfamily member 12), NCR1 (natural cytotoxicity triggering receptor) and IL-6, which were widely used in our signatures, were not included in the pancreatic ductal adenocarcinoma signature." (PMID 36699667, 2022).
tendinopathy (39 papers, 2012 to 2025). "As inflammation is an underlying mechanism of tendinopathy pathogenesis, mitochondrial transfer suppressed the levels of pro-inflammatory markers (IL-1β, IL-6, and TNF-α), revealing a promising therapeutic strategy against inflammatory." (PMID 37101277, 2023). "Inflammation is the primary pathogenic mechanism of tendinopathy, and mitochondrial transplantation suppressed NF-κB signaling along with pro-inflammatory marker (IL-1β and IL-6) levels." (PMID 33925007, 2021). "TNFα alone can also trigger the IL-6 expression in the tenocytes and also a higher expression of IL-6 has been associated with tendinopathy." (PMID 33803624, 2021). "Network-based assessment indicated that key targets associated with NGR1 in treating tendinopathy may potentially include IL-6, TNF, and MMP9." (PMID 40697661, 2025). "Using the assembloid model, we investigated whether IL-6 signaling could play a causative role in the hypercellularity that is a major hallmark of tendinopathy." (PMID 39918402, 2025). "In our study, the difference of serum levels of IL-6, IL-15, IL-33, and IL-17 are noted before and after serum biomarkers can reflect systemic inflammatory responses, metabolic changes, and tissue remodeling associated with tendinopathy." (PMID 39690426, 2024). "Our data partially support this hypothesis, given the negative relationships observed between AT CSA and pro-inflammatory cytokines TNF-α, IL-6 and IL-1β, all have been associated with the development of tendon disorders." (PMID 33484409, 2021). "IHC staining revealed that NGR1 exhibited a dose-dependent therapeutic effect on tendinopathy, including reducing the expression of the inflammatory cytokine IL-6, downregulating Col3 and MMP3 expression, and upregulating Col1 expression at 5 weeks." (PMID 40697661, 2025). "So far, our results have shown that IL-6 signaling enhances proliferation and migration of fibroblasts toward the tendon core and that the presence of fibroblasts invokes tendinopathy-like changes in the tendon core in vitro." (PMID 39918402, 2025). "IL‐6 was found to actively being involved in the development of tendon disease and tendon tears, alongside an array of other cytokines." (PMID 39801753, 2025). "Both in rat cultured tenocytes and in Achilles’ tendons with collagenase-induced tendinopathy levels of IL6, ROS and NOX1 and NOX4 were increased while SIRT1 and SIRT6 were decreased together with SOD activity." (PMID 40023978, 2025). "Vice versa, we show that these reparative fibroblasts promote the development of tendinopathy hallmarks in the damaged explant upon IL-6 activation." (PMID 39918402, 2025). "To this end, we harnessed an in vitro assembloid model of inter-compartmental crosstalk to better dissect the role of IL-6 in tendinopathy." (PMID 39918402, 2025). "IL-6 increases glycosaminoglycan degradation in cartilage and promotes pathologic fibroblast activity in tendinopathy." (PMID 41185633, 2025). "By intersecting the targets of NGR1 with those associated with tendinopathy, we constructed a PPI network, and the results showed that targets such as IL-6, TNF, AKT1, MMP9, and MMP3 are valuable in assessment." (PMID 40697661, 2025). "We conclude that IL-6 activates tendon fibroblast populations which then initiate and deteriorate tendinopathy hallmarks." (PMID 39918402, 2025). "Upregulation of inflammatory mediators (e.g., IL1β, IL1, IL6, and tumor necrosis factor-α) strongly suggests that inflammation is a key process in tendinopathy." (PMID 35689230, 2022). "qRT-PCR results showed that the expression of inflammatory cytokines Il-1b, Il-6 and Tnfa significantly increased during tendinopathy, and this enhancement was reversed by FR treatment in the CIT group." (PMID 35458235, 2022). "The expression of IL6 in the Achilles tendon of the collagenase-induced tendinopathy model was significantly suppressed following 2 weeks of NMN treatment compared to the control group (p < 0.0001)." (PMID 35287653, 2022).